ORAI1 (ORAI calcium release-activated calcium modulator 1)
Diseases named in the same sentence as ORAI1 in open-access papers (continued):
Sharing a sentence is not in itself a finding about the gene and the disease.
infection (10 papers, 2013 to 2023). The state of being infected such as from the introduction of a foreign agent such as serum, vaccine, antigenic substance or organism. "Lung histology at day 14 post-infection (p.i.)showed comparable pulmonary inflammation and alveolar volume in Orai1/3-deficient and littermate control mice." (PMID 36803766, 2023). "Knockdown of Orai3 transcripts however required the use of a multiplicity of infection (moi) of adenovirus (moi 250), significantly higher than that required to achieve knockdown of Orai1 and Orai2 transcripts (moi 100)." (PMID 24040356, 2013). "All infected WT and Orai1/3-deficient mice survived and experienced a similar reduction in body weight over the two week-course of infection (not shown)." (PMID 36803766, 2023). "We showed that lentivirus-Orai1 shRNA infection could knockdown of Orai1 expression in coronary artery SMCs, which attenuated 5-HT-elicited Ca2+ influx." (PMID 25202989, 2014). "As anticipated, at 4 hours post infection, STIM1 and Orai1 were found to redistribute within their respective membranes and appear as “puncta”, indicating the formation of closed ER-PM CSs and the opening of SOCE channels in PRRSV-infected cells." (PMID 36972295, 2023). "In agreement with the results presented previously, HG treatment failed to disrupt cytoskeleton and form the cortical F-actins in HPCs infected with Orai1 CRISPR-Cas9 LV, but did in HPCs with CT LV infection." (PMID 35490782, 2022). "Activated STIM1 interacted with Orai1 and activates CRAC channels, thereby increasing the Ca2+ level in the ER and promoting vvIBDV infection, which could be abolished by the inhibition of CRAC channels." (PMID 35891504, 2022).
cardiovascular disease (7 papers, 2012 to 2026). "While controversy remains as to the importance of SOCE in excitable cells, STIM1 and Orai1 are essential for cellular homeostasis and their disruption is linked to various diseases associated with aging such as cardiovascular disease and neurodegeneration." (PMID 35821821, 2022). "Another possibility is that SOCE mediated by STIM1 and Orai1 is involved in the pathophysiology of cardiovascular diseases." (PMID 22984609, 2012). "Therefore, although we do not see a role for ASIC1a and Orai1 in basal SOCE responses in mesenteric arteries, these channels may exhibit a larger role in the enhanced SOCE response associated with cardiovascular diseases." (PMID 32702049, 2020).
cardiac disease (5 papers, 2020 to 2026). "Hence, Orai1-mediated SOCE may be a novel therapeutic target to consider in heart disease." (PMID 33117812, 2020).
adenocarcinoma (4 papers, 2021 to 2024). A common cancer characterized by the presence of malignant glandular cells. "Altogether, our results indicate that Lacticaseibacillus paracasei and Lactiplantibacillus plantarum postbiotics attenuate SOCE by reducing Orai1 and STIM1 expression in adenocarcinoma cell lines without having any significant effect on SOCE in normal colon mucosa cells." (PMID 38514909, 2024).
bacterial infections (3 papers, 2016 to 2021). "Patients with CRAC channelopathy due to LOF mutations in ORAI1 and STIM1 suffer from life‐threatening viral and bacterial infections early in life." (PMID 32609955, 2020).
metabolic disorder (2 papers, 2022 to 2026). "The present studies identified a critical role for ORAI1 on Th17 cell differentiation and pathogenicity through the control of mitochondrial function under a metabolic disorder characterized by elevated concentrations of fatty acids in the circulation." (PMID 35663942, 2022).
brain disorder (1 paper, 2023). A disease affecting the brain or part of the brain. "Challenges ahead will be to investigate the roles and function of TGM1, TGM2, ATF3, RCN3, ORAI1, and ITPR3 in TBI as well as TBI-induced secondary brain disorders." (PMID 37645012, 2023).
hematologic malignancies (1 paper, 2018). "Alterations of Orai1 and even more STIM1 in solid cancers have been exhaustively studied but, to our knowledge, no data are available concerning the expression of these proteins in hematologic malignancies." (PMID 30373149, 2018).
infectious disease (1 paper, 2022). A disorder directly resulting from the presence and activity of a microbial, viral, or parasitic agent in humans. "STIM1 and ORAI1 constitute the core machinery of the ubiquitous SOCE pathway and loss of function in these proteins is associated with severe immune and muscular disorders and infectious diseases." (PMID 36321903, 2022).
lung (1 paper, 2016). "In the human lung ADC tissue samples, we observed higher levels of Orai1 expression in the FGF4 strong expression group than in the weak and negative expression groups." (PMID 27677589, 2016). "Finally, 60 human lung ADC samples and 21 sets of matched specimens (primary and metastatic foci in lymph nodes from one patient) were used to confirm the clinicopathologic significance of FGF4 and its correlation with E-cadherin, Vimentin and Orai1 expression." (PMID 27677589, 2016).
ORAI1 also shares sentences with these, for which no sentence is quoted: ectodermal dysplasia (9 papers); muscular disease (4); pneumonia (4); epilepsy (3); neurodegenerative disease (3); skeletal muscle disorder (3); Allergy (2); Alzheimer disease (2); colorectal tumor (2); congenital myopathy (2); dermatitis (2); diabetes (2); graft versus host disease (2); Hypertension (2); inflammation (2); Kaposi's sarcoma (2); multiple sclerosis (2); Myalgia (2); neck carcinoma (2); Non-alcoholic Fatty Liver Disease (2); renal cell carcinoma (2); skin melanoma (2); uterine carcinoma (2); acute lung injury (1); acute respiratory distress syndrome (1); alopecia (1); amyotrophic lateral sclerosis (1); autoimmune hemolytic anemia (1); autoimmune lymphoproliferative syndrome (1); brain hemorrhage (1).
A further 58 diseases each share a sentence with ORAI1 in 1 paper.